SLIT1 (slit guidance ligand 1)
Description:
Thought to act as molecular guidance cue in cellular migration, and function appears to be mediated by interaction with roundabout homolog receptors. During neural development involved in axonal navigation at the ventral midline of the neural tube and projection of axons to different regions (By similarity). SLIT1 and SLIT2 together seem to be essential for midline guidance in the forebrain by acting as repulsive signal preventing inappropriate midline crossing by axons projecting from the olfactory bulb.
Synonyms: Slit-1; MEGF4; SLIL1; SLIT3
Tractability: Small molecule: it belongs to a druggable protein family. Antibody: UniProt places it where antibodies can reach, with medium confidence; UniProt predicts a signal peptide or a membrane-spanning region; its Gene Ontology location is reachable by antibodies, with medium confidence; the Human Protein Atlas places it where antibodies can reach. PROTAC: ubiquitination databases record sites on it; its protein half-life has been measured.
Safety:
Unwanted effects reported when the protein is acted on. In parentheses: how it was acted on, where the effect was seen, and who reports it.
drug toxicity (source: ClinPGx)
Gene: Protein-coding gene on chromosome 10 (96,998,038 to 97,185,959, reverse strand). Ensembl gene ENSG00000187122.
Subcellular location: Secreted
Subcellular location (Human Protein Atlas): Plasma membrane; Predicted to be secreted
Pathways (Reactome):
Developmental Biology: Netrin-1 signaling; Regulation of commissural axon pathfinding by SLIT and ROBO; Regulation of cortical dendrite branching; Regulation of expression of SLITs and ROBOs; Signaling by ROBO receptors
Gene Ontology:
Molecular function: protein binding; Roundabout binding; calcium ion binding; heparin binding; heparan sulfate proteoglycan binding
Biological process: axon extension involved in axon guidance; axon guidance; chemorepulsion involved in embryonic olfactory bulb interneuron precursor migration; motor neuron axon guidance; negative chemotaxis; forebrain morphogenesis; negative regulation of synapse assembly; negative regulation of axon extension involved in axon guidance; spinal cord development
Cellular component: extracellular region
Genetic constraint (gnomAD): Loss-of-function variants: 58 observed, 167.43 expected, observed/expected ratio (o/e) 0.35, 90% interval 0.28 to 0.43. The upper end of that interval is the gene's LOEUF score, 0.43, which puts it in group 1 of 6, group 1 being the genes least tolerant of losing a copy. Missense variants: 1,591 observed, 1,991.2 expected, observed/expected ratio (o/e) 0.8, 90% interval 0.77 to 0.83. Synonymous variants: 736 observed, 819.68 expected, observed/expected ratio (o/e) 0.9, 90% interval 0.84 to 0.95.
Homologues: Orthologues: chimpanzee SLIT1 (99% identical), macaque SLIT1 (99% identical), pig SLIT1 (96% identical), dog SLIT1 (95% identical), mouse Slit1 (94% identical), rat Slit1 (94% identical), guinea pig SLIT1 (94% identical), rabbit SLIT1 (90% identical), tropical clawed frog slit1 (82% identical), zebrafish slit1a (74% identical), zebrafish slit1b (67% identical). Paralogues in human: SLIT2 (66% identical), SLIT3 (59% identical), TLR9 (11% identical), SLITRK5 (10% identical), LRRN1 (10% identical), LRFN5 (10% identical), LRRN3 (10% identical), SLITRK6 (10% identical), SLITRK3 (10% identical), LRRN2 (10% identical), SLITRK4 (10% identical), LRFN3 (10% identical), and 13 more.
Diseases named in the same sentence as SLIT1 in open-access papers:
SLIT1 is named in the same sentence as 32 diseases in open-access papers, as found by Europe PMC text mining. Sharing a sentence is not in itself a finding about the gene and the disease. The quoted sentences say what the papers report.
colorectal cancer (10 papers, 2004 to 2025). A primary or metastatic malignant neoplasm that affects the colon or rectum. "Specifically, ADAMTS18 has been implicated in tumorigenesis in melanoma and colorectal cancers, while SLIT1 functions as a tumor suppressor in breast epithelium." (PMID 40868176, 2025). "SUV39H2 directly binded to the SLIT1 promoter, suppressing SLIT1 transcription to enhance proliferation and metastasis in colorectal cancer." (PMID 37306883, 2023). "Another study showed that SUV39H2 promotes colorectal cancer proliferation and metastasis via tri-methylation of the SLIT1 promoter and suppression of SLIT1 transcription." (PMID 34357075, 2021). "Analogously, SUV39H2 was reported to be recruited on the promoter of SLIT1 and promote the proliferation and metastasis of colorectal cancer, suggesting that the epigenetic modulation of SUV39H2 was of importance." (PMID 30348215, 2018). "In colorectal cancer cells, Slit1 can inhibit both proliferation and migration." (PMID 39768930, 2024). "For example, an abnormal dopaminergic commissure at the level of the diencephalon traveling through the hypothalamus from the MFB has been previously reported in the Slit1/Slit2 double KO, the Deleted in colorectal cancer (Dcc) KO, and the NK2 Homeobox 1 (Nkx2.1) KO mice." (PMID 27648578, 2016).
glioma (5 papers, 2004 to 2024). A benign or malignant brain and spinal cord tumor that arises from glial cells (astrocytes, oligodendrocytes, ependymal cells). "To investigate the underlying mechanism of miR-640 inhibition of SLIT1 in radiation-resistant glioma, we analyzed the Wnt/β-catenin signaling pathway." (PMID 35996510, 2022). "Knocking down SLIT1 caused suppression of the Wnt/β-catenin signaling pathway, indicating that miR-640 restricts the Wnt/β-catenin signaling pathway by targeting SLIT1 to promote glioma radiosensitivity." (PMID 35996510, 2022). "For instance, in glioma cell lines, the knockdown of Slit1 results in the suppression of Wnt/β-catenin signaling pathway, subsequently leading to decreased cell proliferation and adhesion." (PMID 39768930, 2024). "In 34 glioma tissues collected from our patients, the expression of miR-640 decreased in glioma tissues, and it negatively correlated with SLIT1 expression in the glioma." (PMID 35996510, 2022). "In conclusion, miR-640 enhances the radiosensitivity of glioma cells by inhibiting SLIT1 and restraining the Wnt/β-catenin signal pathway." (PMID 35996510, 2022). "The cell lines were transfected with si-SLIT1 or miR-640 inhibitor to study the radiosensitivity of glioma cells." (PMID 35996510, 2022). "Compared with normal tissues, SLIT1 mRNA and protein expression levels in glioma tissues were significantly elevated by approximately 3.5- and 1.8-fold, respectively." (PMID 35996510, 2022). "We also quantified the expression of miR-640 and SLIT1 with RT-qPCR to assess how it correlates in glioma tissues." (PMID 35996510, 2022). "We selected 4 Gy as the fixed radiation dose and further studied SLIT1 effects on glioma radiosensitivity." (PMID 35996510, 2022). "Our results suggest that SLIT1 is upregulated in glioma, plays a vital role in promoting glioma development, and is a molecule conferring radiation resistance." (PMID 35996510, 2022). "To assess the influence of SLIT1 on the apoptosis of glioma cells, we analyzed the activity of caspase-3 in the U251 and A172 cell lines." (PMID 35996510, 2022). "To elucidate the relationship between SLIT1 and glioma radiation resistance, we knocked down SLIT1 in the U251 and A172 cell lines." (PMID 35996510, 2022). "Next, we treated U251 and A172 cell lines with different doses of X-rays to explore their effect on SLIT1 expression in glioma cells." (PMID 35996510, 2022). "SLIT1 expression in glioma tissues and cell lines negatively correlated with miR-640, indicating that miR-640 inhibits SLIT1." (PMID 35996510, 2022). "In conclusion, miR-640 inhibits radio-resistance of glioma, where SLIT1 and Wnt/β-catenin play a central role." (PMID 35996510, 2022). "Since SLIT1 expression is neuronal specific, we analysed the methylation status of the 5′ CpG island of the SLIT1 gene in glioma tumour cell lines and primary tumours by COBRA and direct sequencing of bisulphite-modified DNA." (PMID 15534609, 2004). "SLIT1 expression was restored/upregulated in five glioma tumour lines (methylated for SLIT1) by treatment with 5-aza-2′-deoxycytidine." (PMID 15534609, 2004). "In addition, we observed radiation-induced SLIT1 expression and detected SLIT1 silencing-induced radio-sensitization of the tested glioma cell lines." (PMID 35996510, 2022). "Therefore, we conclude that down-regulating miR-640 reduced radiosensitivity of glioma cells, and relieved the effect of si-SLIT1 on radiosensitivity of glioma cells." (PMID 35996510, 2022). "To explore whether miR-640 and SLIT1 negative regulatory relationship has a practical effect on the radiosensitivity of glioma, we performed a CCK-8 assay and showed that the cell viability of U251 and A172 cells decreased with increasing radiation doses." (PMID 35996510, 2022). "In this study, we analyzed how SLIT1 affects glioma radiation tolerance." (PMID 35996510, 2022).
glioma (continued). "Furthermore, we examined SLIT1 expression in glioma cells and found that it was increased in U251 and A172 cells compared with that in healthy NHA cells." (PMID 35996510, 2022). "This tumor-suppressive feature of the SLIT1 gene has also been observed in gliomas." (PMID 35996510, 2022). "Aiming at the up-regulation of SLIT1 expression in glioma cells and the change of SLIT1 expression under the action of radiation, we further studied the role of SLIT1 in the malignant behavior and radiosensitivity of glioma cells through CCK-8, wound healing, and transwell assays." (PMID 35996510, 2022). "Because the Wnt/β-catenin signaling pathway is usually active in the glioma, we investigated whether miR-640 inhibition and SLIT1 silencing affect GSK-3β, Wnt, or β-catenin expression." (PMID 35996510, 2022). "In addition, we found that EGFR had higher transcription and protein expression levels compared with those for SLIT1 in gliomas characterized as WHO III in patients >40 years." (PMID 34123829, 2021). "While SLIT1 gene is frequently methylated in glioma tumour lines but at low frequencies in glioma tumours, hence SLIT1 may play a role in late gliomagenesis." (PMID 15534609, 2004). "Whether miR-640 and SLIT1 are involved in glioma radiation tolerance is unknown." (PMID 35996510, 2022). "Moreover, miR-640-mediated inhibition of SLIT1 promotes the radiosensitivity of glioma cells." (PMID 35996510, 2022). "Therefore, the miRNA network upstream of SLIT1 and other possible miR-640 targets (e.g., SLIT2 and SLIT3 mRNAs) related to glioma radiation resistance requires further exploration." (PMID 35996510, 2022). "To define the biological role of SLIT1 in radiation-resistant glioma, we first analyzed its expression in glioma and adjacent normal tissues from the patients who underwent radiotherapy using RT-qPCR and western blotting." (PMID 35996510, 2022).
pancreatic cancer (3 papers, 2015 to 2026). "Lactate promotes histone H3K18 lactylation, increasing the transcription of neural invasion‐associated genes such as L1CAM and SLIT1, thereby driving PNI in pancreatic cancer." (PMID 41556039, 2026). "This included elements of the Hedgehog signaling pathway (SHH, GAS1), semaphorin signaling (SEMA3A, PLXNA1, PLXNB2, PLXND1, PLXNA2, FARP1, FARP2) and also axon guidance pathways (ROBO1, SLIT1, SLIT3 and SLITRK2), all notable for their involvement in pancreatic cancer progression and metastasis." (PMID 36429078, 2022).
dyslexia (2 papers, 2021 to 2024). A learning disorder characterized by an impairment in processing written words. "Also, SLIT1 is thought to be associated with the development of dyslexia because it is responsible for preventing unwanted midline crossing of axons by acting as the molecular guidance cue in cellular migration." (PMID 34674647, 2021). "However, it is not yet clear how SLIT1 and SRGAP1 are directly involved in the development of dyslexia." (PMID 34674647, 2021).
lung carcinoma (2 papers, 2022 to 2025). "SLIT1 expression is specific to brain and the nervous system and its hypermethylation has not been reported in lung cancer." (PMID 35053460, 2022).
melanoma (2 papers, 2018 to 2025). A malignant, usually aggressive tumor composed of atypical, neoplastic melanocytes. "Four Robo receptors (Robo1 to Robo4) and three Slit ligands (Slit1 to Slit3) are present in melanocyte and melanoma cells, whereas only Robo1, Robo3 and Slit1 are present in E15.5 mouse melanoblasts." (PMID 29769218, 2018).
schizophrenia (2 papers, 2023 to 2024). A major psychotic disorder characterized by abnormalities in the perception or expression of reality. "There was a highly significant set=level association with schizophrenia (P = 6.31 × 10−9), with 21 genes individually associated at P < 0.05 including BHLHE22 but not SLIT1 or SLIT2." (PMID 39133845, 2024).
Stroke (2 papers, 2021 to 2025). Sudden impairment of blood flow to a part of the brain due to occlusion or rupture of an artery to the brain. "In an experimental stroke model, neuroblasts overexpressing Slit1 were transplanted into the post-stroke brain." (PMID 41531492, 2025).
adenoma (1 paper, 2020). A neoplasm arising from the epithelium. "In GH-, PRL- and TSH-secreting adenomas genes such as SLIT1, PRLR and miR377 were upregulated due to demethylation." (PMID 33168897, 2020). "SLIT1 was particularly more up-regulated in TSH-, GH- and PRL-secreting adenomas (7.16) than in ACTH-adenomas (0.425) or non-functioning adenomas (0.172), (p = 0.0001)." (PMID 33168897, 2020).
aortic regurgitation (1 paper, 2023). "In regards to BAV adult patients with variants in ROBO1, ROBO2, SLIT1 and SLIT3 genes, the presence of BAV-related complications such as aortic regurgitation, aortic stenosis, and AscAA was checked." (PMID 36855159, 2023).
aplastic anemia (1 paper, 2015). Anemia resulting from bone marrow failure (aplastic or hypoplastic bone marrow). "In addition, missense mutations in SLIT1 have been connected to aplastic anemia (AA), a rare but life-threatening bone marrow failure syndrome, which also support the role of SLIT1 in early hematopoiesis." (PMID 26225558, 2015).
cervical cancer (1 paper, 2011). A primary or metastatic malignant neoplasm involving the cervix. "Hypermethylation at the promoters of genes (SLIT1, SLIT2, SLIT3, ROBO1, and ROBO3) involved in Slit-Robo pathway resulting in down-regulated gene expression was also indentified in invasive cervical cancer." (PMID 22140553, 2011).
cyclopia (1 paper, 2017). "Interestingly, the loss of slit-1, not its expansion, is typically associated with a reduction in brain size and cyclopia like that we observe after miR-124 KD." (PMID 28807895, 2017).
gastric tumor (1 paper, 2025). "During early gastric tumor progression, methylation of CpG islands inactivates SLIT1, SLIT2 and SLIT3." (PMID 40508075, 2025).
glioblastoma (1 paper, 2024). The most malignant astrocytic tumor (WHO grade IV). "For example, in glioblastoma, the overexpression of Slit1 leads to reduced cell proliferation, adhesion, and viability." (PMID 39768930, 2024).
squamous cell carcinoma (1 paper, 2022). A carcinoma arising from squamous epithelial cells. "Hypermethylation of three CpGs (cg13261825, cg03260566 and cg01663016) in SLIT1, SLIT2 and SLIT3 genes was found at a higher prevalence in adenocarcinoma than in squamous cell carcinoma, although the difference was not statistically significant." (PMID 35053460, 2022).
tumor (12 papers, 2004 to 2025). "The present study focused on GDF1 because it is closely linked to poor tumor differentiation, while SLIT1 possesses significant oncogenic potential and is responsible for the development and metastasis of various types of cancers." (PMID 36364024, 2022). "Other candidate tumor suppressor genes gene such as SLIT1, SEZ6L and MYO18B, were deleted in EOBRCA and consequently downregulated at the gene expression level, as reported in other solid tumors." (PMID 36352274, 2022). "We analysed the 5′ CpG island of SLIT3 and SLIT1 genes in tumour cell lines and primary tumours for hypermethylation." (PMID 15534609, 2004). "In addition, we also analyzed tumor angiogenesis genes, and the results showed that seven tumor angiogenesis genes (HIF1A, PDGFB, NRP1, VEGFB, FGFR1, ROBO1, and SLIT1) had substantially higher expression in the high-risk group compared with the low-risk group." (PMID 35311113, 2022). "As we can see in our results, SLIT1 and SLIT2 are more expressed in the PTEN model, which presents a more advanced tumor characterized by stromal invasion." (PMID 40508075, 2025). "To identify differentially methylated CpGs at the promoter regions of SLIT genes, we analyzed methylation statuses of SLIT1, SLIT2 and SLIT3 genes in tumor and matched normal tissues from 42 NSCLC patients previously reported." (PMID 35053460, 2022). "CIMP status was predicted using an established array-based marker panel of CIMP, including B3GAT2, FOXL2, KCNK13, RAB31, and SLIT1, that was shown to identify CIMP+ (CIMP-H or CIMP-L) tumours with 100% sensitivity and 95.5% specificity, with 2.4% misclassification." (PMID 27846243, 2016). "We performed IHC to analyze the expression and localization of SLIT1, SLIT2, and ROBO2 proteins in human PCa and non-neoplastic samples adjacent to the tumor." (PMID 40508075, 2025). "Five CpGs at the CpG island of SLIT1, SLIT2 or SLIT3 genes were significantly (Bonferroni corrected p < 0.05) hypermethylated in tumor tissues obtained from 42 NSCLC patients than in matched normal tissues." (PMID 35053460, 2022).
cancer (6 papers, 2004 to 2025). A tumor composed of atypical neoplastic, often pleomorphic cells that invade other tissues. "For example, Tff3, Hpse, Slit1, Spon1, Spock1, and Spock3 are associated with increased cancer cell invasion and were upregulated in Rreb1-/-, and Selenbp1 and Serpin6b are tumor suppressor genes that were downregulated." (PMID 33929320, 2021). "SLIT1 is tumor suppressor gene and epigenetic suppression of this gene is associated with cancer progression, but loss of this gene might be culpable for development pituitary prolactinoma." (PMID 33709028, 2021). "In this report, we analysed the methylation status of 5′ CpGs islands for the remaining SLIT gene family members (SLIT3 and SLIT1) in human cancers." (PMID 15534609, 2004).
adenocarcinoma (2 papers, 2022 to 2025). A common cancer characterized by the presence of malignant glandular cells. "In our study, we observed increased expression of SLIT1 and SLIT2 in the Pten model, which develops advanced-stage adenocarcinomas with prominent stromal invasion." (PMID 40508075, 2025).
SLIT1 also shares sentences with these, for which no sentence is quoted: breast carcinoma (3 papers); depression (3); alcohol dependence (1); aortic stenosis (1); astrocytoma (1); bone marrow failure syndrome (1); central neurocytoma (1); colon cancer (1); coronary heart disease (1); infection (1); pancreatitis (1); peripheral nerve injury (1); prostate tumors (1).